MMP2 (matrix metallopeptidase 2)
Diseases named in the same sentence as MMP2 in open-access papers (continued):
Sharing a sentence is not in itself a finding about the gene and the disease.
pancreatic cancer (200 papers, 1996 to 2025). "Overexpression of miR-21 in pancreatic cancer cells is positively associated with the overexpression of invasion-related genes, including MMP-2, MMP-9 and vascular endothelial growth factor (VEGF)." (PMID 32489562, 2020). "Co-expression of TNC and MMP9 or MMP2 was associated with a poorer prognosis and was found to be an independent predictor of survival for pancreatic cancer patients." (PMID 29088796, 2017). "Previous studies have shown that inhibition of GSK3β reduced the proliferation and survival of pancreatic cancer cells, which was associated with decreased cyclin D1 expression, Rb phosphorylation and secretion of matrix metalloproteinase-2 (MMP-2)." (PMID 26213494, 2015). "In a research conducted on 6 cell lines, it was shown that increased expression and activity of MMP2 are associated with greater invasive potential of pancreatic cancer cells." (PMID 23304126, 2012). "IL-8 overexpressed in pancreatic cancer increases MMP-2 activity and plays an important role in the invasiveness of human pancreatic cancer, and human pancreatic cancer is associated with increased expression of IL-8." (PMID 22235381, 2011). "For instance, RECK expression in pancreatic cancer tissue was significantly lower than in adjacent normal tissues and was negatively associated with MMP-2 activation and tumor invasive ability." (PMID 19995435, 2009). "Our data suggest that Cav-1 deficiency in PSCs is conducive to primary pancreatic cancer growth through upregulated paracrine cytokine signaling (including shh/MMP2/bFGF/IL-6) and that ROS play a vital role in the interaction between PSCs and pancreatic cancer cells." (PMID 32377291, 2020). "It has been shown that MMP2 is associated with the progression of pancreatic cancer and could be a therapeutic target." (PMID 31824949, 2019). "The CCLE dataset revealed elevated expression of six module genes (GFPT2, MFAP5, CTSK, MMP2, FSTL1, and PRRX1) associated with poor overall survival in patients with pancreatic cancer." (PMID 40430018, 2025). "Gal-3 promotes the migration and invasion of human pancreatic cancer cells and tongue cancer cells in vitro by increasing Akt phosphorylation and β-catenin transcriptional activity, leading to enhanced MMP-2 and -9 mRNA and protein expression." (PMID 40566589, 2025). "Elevated MMP2 levels have been observed in various cancers, including breast, lung, and pancreatic cancers." (PMID 39833941, 2025). "According to recent studies, Fascin-1 enhances the invasive ability of pancreatic cancer and liver cancer cells by increasing the expression of MMP2 and MMP9, which are primarily responsible for the degradation of Type IV collagen." (PMID 38921985, 2024). "The utilization of pirfenidone-loaded MMP2-responsive liposomes significantly enhanced gemcitabine penetration to the MMP2-rich pancreatic tumor site in a combinatorial strategy." (PMID 39199647, 2024). "Consistent with this possibility, inhibiting MMP2 activity has been considered as a PPARγ‐independent mechanism for thiazolidinediones to reduce invasiveness of pancreatic cancer cells." (PMID 39636301, 2024). "A previous study has shown that thiazolidinediones reduced the transcription of MMP2 in pancreatic cancer cells." (PMID 39636301, 2024). "It downregulates the levels of HIF-1α, GLUT-1, and VEGF in pancreatic carcinoma and inhibits the level of MMP-2, MMP-9, uPA, and VEGF in TRAMP mouse by downregulating IGF-I/IGFBP-3 signaling." (PMID 38611849, 2024). "Okada et.al showed that NGF promoted MMP-2 expression and accelerated the invasion of human pancreatic cancer by activating the MAPK pathway." (PMID 36522730, 2022). "Anti-tumor effect of RA occurs via regulation of the miR-506/MMP2/16 axis in pancreatic tumor cells." (PMID 36247004, 2022).
pancreatic cancer (continued). "With the development of protein molecular technology and proteomics, several serum protein molecules characteristic of early pancreatic cancer have been identified, including matrix metalloproteinase MMP-2, MMP-9, and serum galactoagglutinin-3." (PMID 36476236, 2022). "Particularly, in PANC-1 pancreatic cancer cells, the combination led to the downregulation of MMP2 and MMP9, both pro-invasive and pro-metastatic metalloproteinases." (PMID 36015440, 2022). "In vivo studies have exposed that RA inhibited the tumor growth dose-dependently of pancreatic cancer cells and enhanced the expression of miR-506, although lowered the MMP2/16 and Ki-67 expression in xenograft nude mice." (PMID 36247004, 2022). "In pancreatic cancer cells, GRh2 also induces apoptosis in Bxpc-3 cells by upregulating Bax, caspase-3, and caspase-9, and downregulating Bcl-2, survivin, cyclin D1, MMP-2, and MMP-9." (PMID 36313365, 2022). "GRh2 also inhibited human pancreatic cancer cell Bxpc-3 migration by downregulating MMP-2 and MMP-9." (PMID 36313365, 2022). "We also revealed the new role of CRABP-II in the regulation of IL8/MMP2/MMP14 pathway to promote pancreatic cancer migration and invasion." (PMID 35260193, 2022). "Previous studies have indicated that PEDF inhibits the expression and activities of MMP-2/9 in the aqueous humor of a proliferative diabetic retinopathy model and in spontaneous pancreatic carcinoma." (PMID 36574366, 2022). "It has been reported that MMP2 activation by MT1-MMP contributes to pancreatic cancer progression and invasion, as both fibroblasts and cancer cells can express these proteases." (PMID 33740019, 2021). "An ECM stiffness-induced activation of an MMP-14 and MMP-2/9 cascade has been shown for pancreatic cancer cells and supports our new finding of ECM-triggered MMP activation in BM-covered breast acini." (PMID 33921304, 2021). "Overexpression of hsa_circRNA_001587 significantly decreased abilities of pancreatic cancer cell proliferation, migration, invasion, angiogenesis and tumorigenesis through inhibition of oncogenic MMP-2, MMP-9, MCM2, and VEGF expression in pancreatic cancer." (PMID 34439315, 2021). "The inhibition of MMP-2/9 reduces tumor invasion and metastasis in cervical cancer cells, pancreatic cancer, and choriocarcinoma." (PMID 33805658, 2021). "GSK-3β inhibition in pancreatic cancer cells leads to perturbations in Rac1 and F-actin subcellular localization, reduced production of MMP-2, and decreased phosphorylation of FAK, leading to inhibition of cell migration and invasion." (PMID 34356465, 2021). "LRH-1 spurs pancreatic cancer metastasis by enhancing the transcriptional activity of β-catenin and upregulates downstream targets (c-Myc, MMP2/9)." (PMID 33791301, 2021). "GSK-3β is implicated in cell invasion and metastasis in pancreatic carcinogenesis as its overexpression leads to CXCR4 upregulation and increased MMP-2 expression and results in increased invasiveness of pancreatic cancer cells." (PMID 34356465, 2021). "In pancreatic cancer, the activation of MMP2 by MT1-MMP has been directly related to its progression and invasion." (PMID 33740019, 2021). "Chronic stress induces pancreatic tumor growth and angiogenesis by upregulated expression of matrix metallopeptidase-2 (MMP-2), MMP-9, and vascular endothelial growth factor (VEGF), mediated by a HIF-1α-dependent β-AR signaling pathway." (PMID 33419318, 2020). "CM from sh-Cav-1 PSCs exhibited upregulated levels of shh, MMP2, bFGF, and IL-6, which exert proliferative, invasive, angiogenic, and inflammatory functions during pancreatic cancer progression." (PMID 32377291, 2020). "In pancreatic cancer cells, down-regulation of FoxM1 reduced the expression of MMP-2 and MMP-9, resulting in the inhibition of migration and invasion." (PMID 32429421, 2020).
pancreatic cancer (continued). "In our study, when mice with pancreatic cancer were treated with a selective inhibitor of MMP-2 and MMP-9, SB-3CT, tumor volume and the number of metastases significantly decreased." (PMID 33251135, 2020). "We reveal that Cav-1-silenced PSCs facilitated the growth of pancreatic cancer cells via enhanced paracrine shh/MMP2/bFGF/IL-6 signaling." (PMID 32377291, 2020). "Li et al16 have reported that activation of PPARγ can up‐regulate the tumour suppressor gene PTEN, thereby inhibiting the expression of MMP‐2, thus impairing the migration and invasion of pancreatic cancer cell lines." (PMID 33164330, 2020). "Knockdown of OTX1 expression suppressed pancreatic cancer cell migration and invasion, with down-regulated MMP2 and MMP9 expression." (PMID 32549762, 2020). "GSK2606414 has been shown to inhibit growth of pancreatic cancer cells while also restoring MMP-2 protein accumulation suppressed by ER stress in JEG-3 cells." (PMID 32117210, 2019). "To further investigate the functions of GnRH in tumor invasion and migration of pancreatic cancer cells, we examined the expression levels of MMP2 and MMP9 proteins in GnRH-OE, GnRH-KD, and Control group Panc1 cells." (PMID 31263453, 2019). "Our study was the first to verify the role of TGFß-RI and MMP-2 in CTCs from patientswith pancreatic cancer, showing the relevance of MMP-2 expression in these cells." (PMID 31038558, 2019). "In pancreatic cancer, MMP-2 is produced and secreted by both tumor and stromal cells, and a strong correlation between MMP-2 expression and the invasive potential of pancreatic cell lines has been observed." (PMID 30301152, 2018). "Studies have found that downregulation of FoxM1 in pancreatic cancer cells reduced the expression of MMP-2 and MMP-9, thereby inhibiting pancreatic cancer cell migration and invasion." (PMID 30580327, 2018). "Our study investigated that when overexpressed DDR1 in TM4SF1-silenced cells, the number of pancreatic cancer cells with invadopodia and the expression of MMP2 and MMP9 were increased." (PMID 28368050, 2017). "AURKA inhibition reduced the levels of N-cadherin, CD44, vimentin, MMP-2, Slug, and Snail, but increased E-cadherin levels in pancreatic cancer cell lines." (PMID 28193222, 2017). "It was reported that TNC expression was correlated with the activation of MMP2 in a co-culture of pancreatic cancer BxPC-3 cells with stromal fibroblasts." (PMID 29088796, 2017). "Although the mRNA of MMP2 was both decreased in two pancreatic cancer cell lines after the silence of PEG10." (PMID 28193232, 2017). "For instance, NFATc1 induced malignant cell growth phenotype in pancreatic cancer cells by upregulating Myc and promoted metastasis of mammalian cancer cells via MMP-2 upregulation." (PMID 27259269, 2016). "In this study, we demonstrate that LXA4 can effectively attenuate cell invasion and MMP-9/MMP-2 expression in pancreatic cancer by inhibition of intracellular ROS accumulation and ROS-induced ERK activation." (PMID 26649143, 2016). "SDF-1/CXCR4 are thought to promote pancreatic cancer cell invasion by upregulating the expression and activity of MMP-2." (PMID 26213494, 2015). "Previous studies indicated that HOXA10 and HOXA11 regulate expression of MMP-3 and MMP-2, respectively, and both MMPs contribute to migration/invasion of pancreatic cancer cells." (PMID 25912306, 2015). "It was also found that MMP2 activity increased with pancreatic tumor grade, highlighting the important role of MMP2 in the progression of pancreatic cancer." (PMID 26193320, 2015). "SDF-1/CXCR4 and MMP-2 are overexpressed in pancreatic cancer tissues, and have been found to act as prognostic markers in various types of cancer, including pancreatic cancer." (PMID 26213494, 2015).
pancreatic cancer (continued). "In the present study, we found that cantharidin repressed the invasive ability of pancreatic cancer cells and downregulated matrix metalloproteinase 2 (MMP2) expression through multiple pathways, including ERK, JNK, PKC, NF-κB, and β-catenin." (PMID 26135631, 2015). "To elucidate the effect of GSK3β on the expression of CXCR4 and MMP-2 in pancreatic cancer cells, we overexpresses GSK3β in PANC1 and SW-1990 cells." (PMID 26213494, 2015). "Here, we investigated the relationship between GSK3β and CXCR4/MMP-2 in pancreatic cancer cells, in order to further characterize the cellular and molecular mechanisms involved in pancreatic cancer." (PMID 26213494, 2015). "In this study, we demonstrated that GSK3β induced PANC1 pancreatic cancer cell invasion via the CXCR4/MMP-2 pathway." (PMID 26213494, 2015). "TN-C deposition into the extracellular matrix requires the participation of MMP-2 and the resulting deposited TN-C promotes pancreatic cancer progression." (PMID 26770971, 2015). "A recent study showed that single nucleotide polymorphisms of the β2-AR gene were associated with LNM, poor prognosis, and high expression levels of β2-AR, EGFR, VEGF, and MMP-2 in pancreatic carcinoma." (PMID 26526356, 2015). "Inhibition of pancreatic cancer cell metastasis mediated by downregulating the expression of MMP-2 and MMP-9." (PMID 24505326, 2014). "Our data demonstrate that embelin can inhibit/reverse pancreatic tumor metastasis by inducing the expression of E-cadherin and inhibiting its associated transcription factors (Snail, Slug, and ZEB1) and MMPs (MMP-2 and MMP-9)." (PMID 24694877, 2014). "The overexpression and activation of MMP-2 have an adverse correlation with distant lymph node metastasis integrated with the expression of integrin alphaVbeta3 of pancreatic cancer cells." (PMID 24587996, 2014). "We examined pancreatic tumor xenograft by Western blot and found α-Solanine can significantly decrease the expression of MMP-2 and MMP-9." (PMID 24505326, 2014). "MMP-1,-3,-7,-9,-10 and -12 were significantly upregulated in patients with pancreatic cancer (p < 0.0001, respectively), whereas MMP-2 was significantly decreased in the cancer patient group (p < 0.0001)." (PMID 25483099, 2014). "Other evidence has shown that suppression of FOXM1 leads to a reduction in MMP-2 and MMP-9 expression levels in pancreatic cancer cells, which is associated with an overall decrease in cancer cell migration, invasion and angiogenesis." (PMID 23229761, 2013). "The cytokines taking part in ECM degradation, which were observed in the blood of pancreatic tumor patients, are MMP-2 and MMP-9." (PMID 23768069, 2013). "Matrix metalloproteinase (MMP)-2 and MMP-9 are presumed to be associated with the progression and invasion of various types of cancer cells and are highly expressed in pancreatic cancer." (PMID 23833675, 2013). "Immunohistochemical examination of the primary pancreatic cancers showed higher expression of MMP-2 and FAK and tyrosine phosphorylation of FAK in tumor cells than non-neoplastic pancreatic ducts." (PMID 23408967, 2013). "Taken together, the data suggest that α-mangostin inhibited the invasion and metastasis of pancreatic cancer cells by reducing MMP-2 and MMP-9 expression, increasing E-cadherin expression and suppressing the ERK signaling pathway." (PMID 23833675, 2013). "In our research we demonstrated that among many factors influencing tumor microenvironment c-Met receptor, infiltrating macrophagesو and MMP2 have a significant influence on development and invasion of pancreatic cancer." (PMID 23304126, 2012). "Our analysis of activity of MMPs indicates that MMP2 has a greater impact on development of pancreatic cancer." (PMID 23304126, 2012). "Activation and blocking of the Stat3 signaling pathway can affect invasion ability and expression of the VEGF and MMP-2 genes in pancreatic cancer cells." (PMID 20482858, 2010).
pancreatic cancer (continued). "Recent data from our group shows that PSC significantly contribute to MMP-2 secretion in the desmoplasia of pancreatic cancer in vivo and in vitro." (PMID 24281180, 2010). "Matrix Metalloproteinase 2 (MMP2) has been found to be expressed in pancreatic cancers and has been positively correlated with metastasis." (PMID 17181856, 2006). "M204C4 minimizes pancreatic cancer cell invasion by targeting matrix metalloproteinase-2 (MMP-2)." (PMID 40612874, 2025). "In conclusion, our study successfully identified a module of six key genes—GFPT2, MFAP5, CTSK, MMP2, FSTL1, and PRRX1—through Weighted Gene Co-expression Network Analysis (WGCNA) to assess cancer-associated fibroblast (CAF) infiltration in pancreatic cancer (PC)." (PMID 40430018, 2025). "Consistently, NK-1R antagonists, L-733,060 and L-732,138, could also inhibit SP-induced expression of MMP-2 in pancreatic cancer cells and thus impairing cancer migration." (PMID 36177059, 2022). "Likewise, miR-29c suppresses cell migration and invasion by targeting MMP2, and this miRNA has been suggested as a novel marker of pancreatic cancer metastasis." (PMID 34440625, 2021). "Similarly, miR-29c also showed anti metastasis effect in pancreatic cancer, which reduced the invasion and metastasis of pancreatic cancer cells by targeting MMP2 in vitro." (PMID 32192508, 2020). "Some comorbid conditions other than diabetes mellitus such as renal scars, nephrotic syndrome, focal segmental glomerulosclerosis, pancreatic cancer and chronic kidney failure may also affect urine MMP2 and MMP9, TIMP1 and TIMP2 and TGF-β1 concentrations." (PMID 30396876, 2019). "Further investigation showed that the inhibition of GnRH may promote tumor invasion and migration through upregulation of MMP2 expression in pancreatic cancer cells." (PMID 31263453, 2019). "What is more, Rg3 could downregulate the MMP9/MMP2 expression to inhibit vasculogenic mimicry in pancreatic cancer." (PMID 30915362, 2019). "Furthermore, western blot analysis demonstrated that metastatic markers, MMP-9 and MMP-2 were significantly affected in primary pancreatic tumors and other metastatic organs (lung, liver, and spleen)." (PMID 30899425, 2019). "The MMP2 mRNA was both decreased in two pancreatic cancer cell lines after PEG10 knockdown." (PMID 28193232, 2017). "Therefore, the mechanism by which TNC and MMP2 were co-overexpressed in pancreatic cancer tissue needs to be further investigated." (PMID 29088796, 2017). "Therefore, we looked to determine if these pathways were involved in the regulation of invasion and MMP2 expression by cantharidin in pancreatic cancer cells." (PMID 26135631, 2015). "PAR-2 activation may promote the invasion and migration of human pancreatic cancer cells by increasing MMP-2 expression." (PMID 25452809, 2015). "In the present study, we investigated whether cantharidin could repress the invasive ability of pancreatic cancer cells through downregulation of MMP2." (PMID 26135631, 2015). "Many cancers that overexpress cyclooxygenase-2 (COX-2) have been shown to have high intratumoral levels of PGE2, which has been shown to upregulate the invasive potential of pancreatic cancer cells through an ERK/Ets-1-dependent induction of MMP-2 expression and activity." (PMID 26135631, 2015). "To understand whether and which types of MMPs were involved in the pancreatic cancer cell invasion triggered by leptin, we analyzed the expression change of MMP-2, MMP-7, MMP-9 and MMP-13 before and after leptin treatment." (PMID 25948792, 2015). "In a previous study, we found that miR-106a could promote pancreatic cancer cell invasion by upregulating MMP-2 and MMP-9, and we verified that TIMP-2 was the target of the miRNA." (PMID 25883224, 2015).